TERT (telomerase reverse transcriptase)
Diseases named in the same sentence as TERT in open-access papers (continued):
Sharing a sentence is not in itself a finding about the gene and the disease.
cancer (continued). "It has been shown that PITX1 regulates TERT also in cells of other cancer types." (PMID 35267575, 2022). "A pan-cancer study using more than 18,000 cancer samples demonstrated that 22% did not express either TERT or ALT-associated alterations." (PMID 35953846, 2022). "And the genetic duet of BRAF and TERT was related to advanced cancers." (PMID 36713542, 2022). "However, the unstable nature of TERT mRNA and telomerase RNA makes it challenging to reliably analyze direct TERT expression or telomerase activity for cancer diagnosis or monitoring." (PMID 35327529, 2022). "Our study hypothesizes that LTL and TERT expression are surrogate markers of cancer therapy sensitivity, toxicity, and overall patient outcomes." (PMID 36203452, 2022). "In the wild-type cancer cell lines, by contrast, both alleles (regardless of the transcriptional state) were methylated to similarly high levels in the TERT distal promoter." (PMID 36011010, 2022). "Homologous alleles in wild-type cancer cell lines, unlike the genetically altered ones, were symmetrically methylated at high levels in the TERT distal promoter." (PMID 36011010, 2022). "Like promoters of all actively transcribed alleles, the transcribed TERT promoters of all cancer cell lines, regardless of the mutational status, were hypomethylated in the core and proximal promoter." (PMID 36011010, 2022). "In addition, the coexistence of TERT promoter mutations and BRAF V600E is thought to be a strong genetic background for promoting the aggressiveness of human cancers." (PMID 35903534, 2022). "Evidently, the loss of GABPB1 or GABPA is a more potent cancer-driving force that compensates for the lack of TERT upregulation." (PMID 35326537, 2022). "In that case, TERT-expressing cancer cells are recognized and killed by CTLs." (PMID 36713366, 2022). "In total, 80–90% of cancer cells activate TERT and subsequently telomerase to reach immortality." (PMID 36497228, 2022). "However, some data associate DKC1, TERC, TERT, TINF2, and WRAP53 genes with a higher risk of cancer." (PMID 36091172, 2022). "Many conventional cancer treatments aim to develop new drugs targeting TERT." (PMID 35053139, 2022). "Interestingly, TZAP and TERT expression on TCGA data were positively correlated in various cancers, including HCC." (PMID 36556980, 2022). "Most mitochondrial TERT studies have been conducted on telomerase-positive cancer cells." (PMID 35741087, 2022). "TERT is the catalytic subunit of telomerase and is often reactivated in cancer." (PMID 36138075, 2022). "Hence, CCL21 injection activated DCs at the vaccination site and elicited a stronger antitumor immune response against TERT-expressing cancer cells." (PMID 35335881, 2022). "Comparison between cancer cells with and without TERT promoter mutations further showed a bias in allele-specific TERT expression." (PMID 36713366, 2022). "Wild-type cancers commonly display an altered pattern of TERT promoter DNA hypermethylation." (PMID 36011010, 2022). "Genetic studies previously reported that variants in TERT-CLPTM1L genes were related to susceptibility of cancer and non-cancer diseases." (PMID 35847915, 2022). "A systematic analysis of the whole-genome data of 31 cancer types revealed that 22% of cancers have neither TERT expression nor ATRX mutations (8.1% of GBMs and 10.2% of LGGs)." (PMID 35953846, 2022). "Earlier studies have been mainly focused on the molecules controlling TERT transcription in cancer." (PMID 36713366, 2022). "Hence, PITX1 was rather described as a suppressor of TERT expression and telomerase activity in cells of this other cancer type." (PMID 35267575, 2022). "TERT is one of the most common driver oncogenes of HCC with respect to cancer cell immortality." (PMID 35954337, 2022). "Resistance mechanisms in RET-dependent cancers may differ depending on cell type, RET gene mutation, RET expression level, and TERT promoter mutation status." (PMID 35510953, 2022).
cancer (continued). "Developing and applying TERT as a therapeutic target in cancer have become popular research topics." (PMID 35053139, 2022). "Upregulation of TERT was determined to worsen the patient prognosis for multiple cancer types, which may be expected based on reports that telomerase activity increases with upregulation of TERT." (PMID 36497424, 2022). "Moreover, the same authors showed that this isoform, as well as full length TERT, reduces cisplatin-induced apoptosis in cancer cells." (PMID 36499514, 2022). "First, because TERT is often regulated at the allele level, and in most cancer cells not all TERT alleles are transcribed, we looked at the two major allelic methylation patterns from each cell line separately, instead of averaging them together." (PMID 36011010, 2022). "However, the correlation between the enzymatic activity of hTERT and hTERT (TERT) expression levels in cancer remains elusive." (PMID 35094384, 2022). "Knockout of the TERT coding region was also found to inhibit the growth of cancer cells." (PMID 35053139, 2022). "Inactivating TERT has been identified as a viable cancer therapy by Wen and colleagues." (PMID 35328421, 2022). "We therefore hypothesized that serum starvation-induced changes in GABPA and GABPB1 could underlie the relationship between cell proliferation and the regulation of TERT, specifically in TERTp-mutant human cancer cells." (PMID 36130485, 2022). "However, oncogenic events disrupt HERV repression mechanisms, triggering their reactivation and/or accumulation, and TERT induction is one of the drivers for HERV expression in cancer cells." (PMID 36713366, 2022). "TERT is usually overexpressed in up to 90% of human primary cancers." (PMID 35804881, 2022). "The long-read methylation sequencing of cancer cell lines revealed previously unknown differences in TERT methylation pattern and demethylating agent responses between wild-type and genetically altered cancer cell lines." (PMID 36011010, 2022). "Indeed, studies examining the relationship between telomerase activity and transcriptomic alterations in cancer cells have revealed a host of genes whose transcription appears to be directly overseen by TERT, including EGFR and VEGF." (PMID 35159075, 2022). "Moreover, NF-κB acts in conjunction with TGF-β to drive cancer cell dissemination and disease progression, which is potentiated by TERT through its interaction with the TGF-β-responsive TF, ZEB1." (PMID 35159075, 2022). "An isogenic model derived from human-induced pluripotent stem cells has been described very recently and could be used in future studies to understand genetic dependencies of TERT promoter mutant cancers." (PMID 36130485, 2022). "TERT is directly controlled by miR-128 and miR-138 in different cancers." (PMID 33802026, 2021). "TERT is the reverse transcriptase protein core component of the telomerase complex, which promotes elongation and partial maintenance of telomere length in stem cells and stable maintenance of telomere length in more than 90% of cancer cells." (PMID 33555479, 2021). "TERT inhibitors with high potency, which are capable of fully depleting telomerase activity, have been proposed to exert greater selective pressure and overcome resistance in cancer cells." (PMID 34440361, 2021). "Thus, it is suggesting that the CpG methylation-mediated gene regulation has more complicated molecular functions in the regulation of TERT transcription and the cancer progression." (PMID 34489496, 2021). "In addition, other factors, such as transcriptional, posttranscriptional, and epigenetic modifications can affect the activation or silencing of TERT; however, the effects are poorly understood in somatic, cancer, and stem cells." (PMID 34947936, 2021).
cancer (continued). "We focused on two cancer-related transcripts, TERT mRNA and TUG1 lncRNA." (PMID 34083519, 2021). "Epigenetic regulation may be responsible for reversible silencing of TERT in several biological processes including development and differentiation, and increased TERT expression in cancers." (PMID 33802026, 2021). "Moreover, TERT displays multiple activities and is capable of protecting cancer cells from apoptosis stimulated by various insults and facilitating invasion or metastasis by inducing epithelial-mesenchymal transition or other pro-metastatic cascades 9, 27-29." (PMID 34093793, 2021). "Additionally, induced-TERT or activated-telomerase bestows immortality properties to cancer cells by stabilizing their telomere length (TL)." (PMID 33869033, 2021). "However, we clearly demonstrate the presence of subclonal NF2 mutations in three patients, characterized by clonal mutation in other key MPM mutated cancer genes including BAP1, SETD2, and the TERT promoter." (PMID 34261524, 2021). "Although we found that TAF-I is involved in transcriptional activation of TERT in HeLa cells, whether it is specific for HeLa cells or general for other cancer cells is unclear." (PMID 34489496, 2021). "However, the reactivation of TERT expression in many cancers would bypass the checkpoint signaling pathway activated by critical telomere shortening leading to cellular senescence or apoptosis." (PMID 34253690, 2021). "Studies have described polymorphisms that can increase the transcriptional activity of the TERT promoter and thus may promote cancer progression." (PMID 34059744, 2021). "Human telomerase (TERT) is reactivated in approximately 90% of all cancers." (PMID 33713376, 2021). "TERT-targeted immunotherapy has also become the subject of many cancer therapeutic studies." (PMID 34440361, 2021). "Although the exact biological mechanism is still unclear, THOR methylation might play an important role in regulating TERT expression and may be a potential target for cancer treatment." (PMID 34395278, 2021). "TERT is significantly enriched at tRNAMet, tRNAArg, and tRNALys genes, regulating the expression of these tRNAs, thus controlling the rate of protein synthesis in cancer cells and promoting tumorigenesis to a certain extent." (PMID 34660690, 2021). "In cancer, TERT has been shown to bind TCF binding elements (TBEs) to drive c-MYC expression." (PMID 33599797, 2021). "In cancer cells, the TERT gene may act as an oncogene by promoting cell immortality via the telomere-independent proliferation of cancer cells." (PMID 34070093, 2021). "The fact that they are driving events in cancer development rather than passenger events is supported by the high recurrence, specificity, and functional acquisition of non-coding promoter TERT mutations." (PMID 34368047, 2021). "TERT is related to the proliferation, invasion, and migration of various malignant tumor cells." (PMID 34482792, 2021). "Seeing as these cancer types had the highest total TERT expression and TERT_238.6 was the predominant isoform in most samples, this relationship may simply be reflecting one of total TERT expression and telomere re-lengthening." (PMID 33924498, 2021). "The overexpression of Telomerase reverse transcriptase (TERT) occurs in various malignant tumors." (PMID 34482792, 2021). "Further, a subset of cancers shows extremely low TERT expression, possibly suggesting they belong to ALT through mutations outside ATRX or DAXX or to completely unknown telomere maintenance pathways." (PMID 34097189, 2021).
cancer (continued). "In addition to these observations, this study proposes that TAF-I is involved in the occurrence and/or recurrence of cancer cells through the upregulation of TERT transcription as a novel epigenetic regulator." (PMID 34489496, 2021). "In addition to such somatic mutations, amplification of TERT gene and rearrangement of TERT locus directing its transcriptional activation are also reported during cancer development." (PMID 34489496, 2021). "Hypomethylation of the TERT hypermethylated oncological region (THOR, position −649 to −217 from the TSS) allows binding of transcription factors and is associated with TERT reactivation in cancer cell lines." (PMID 34944589, 2021). "Both MYC and SP1 expression correlate with TERT transcription in various cancer cell lines." (PMID 33802026, 2021). "Also, the capacity of cancer cells to grow under anchorage-independent conditions is enhanced by TERT." (PMID 33435156, 2021). "Based on this assumption, TERT-p mutation is suggested as a new potential therapeutic target in non-HPV-related cancer." (PMID 33635430, 2021). "Among the 33 cancer types, eight had at least 25% of samples expressing zero TERT." (PMID 33924498, 2021). "Yet, it is tempting to hypothesize that higher lncRNA TAPAS decrease TERT and ultimately contribute to the selective advantage of −124C>T and its strong overrepresentation across cancers." (PMID 34944589, 2021). "These properties make TERT a potentially attractive biomarker in cancer." (PMID 34858860, 2021). "Similarly, β-catenin was found at the TSS of TERT in adult mouse stem cells, primary mouse neurospheres, and human cancer cell lines, correlating with TERT expression." (PMID 34439356, 2021). "In particular, a 433 bp-long genomic region including 52 CpG sites located upstream of the core promoter in TERT locus, called the TERT hypermethylated oncological region (THOR), is highly methylated and involved in the cancer-associated transcription of the TERT18." (PMID 34489496, 2021). "Studies using strategies of telomerase inhibition have shown that strong TERT inhibition can result in progressive telomere shortening and ultimately to cancer cell apoptosis, including using of small-molecule inhibitors, immunotherapy and antisense oligonucleotides." (PMID 33938397, 2021). "Past studies have confirmed that TERT is upregulated and altered in most cancer patients." (PMID 34026613, 2021). "In addition to telomere content, we also investigated the genomic landscape of telomere maintenance mechanisms, namely mechanisms of TERT reactivation, across cancer cell lines." (PMID 34486523, 2021). "One mechanism comes from the interaction between TERT and a subunit of nuclear factor kappa B (NF-κΒ), suggesting that TERT responds to the regulation of NF-κΒ target genes, such as cytokines involved in cancer progression." (PMID 33763172, 2021). "A combination of TERT and BRAFV600E mutations could be beneficial in the determination of cancers in intermediate nodules in FNAB." (PMID 34684168, 2021). "Notably, TERT expression or its re-induction in the case of iPSC generation, is a marker of ‘stemness’ of potential relevance for maintenance of cancer stem cells." (PMID 34253690, 2021). "Identifying and understanding the noncanonical functions of TERT should provide new and important insights into the role of telomerase in cancer progression, and so help in the development of specific strategies for the therapeutic manipulation of TERT in human cancer." (PMID 33713376, 2021). "The mechanisms that re-activate TERT gene expression in cancer vary in different types of cancers." (PMID 33599797, 2021). "Several cancer-relevant genes, including cyclin A, telomerase reverse transcriptase (TERT), platelet-derived growth factor receptor beta (PDGFRB), and mitogen-activated protein kinase 1 (MAPK1), change their expression following the integration of HBV into host DNA." (PMID 34440678, 2021).
cancer (continued). "Conversely, almost all human cancer cells maintain telomere length over many cell divisions through activating either DNA recombination alternative lengthening of telomeres (ALT) or upregulating TERT." (PMID 34395278, 2021). "Because ALT is most commonly found in these cancer types, this may be a consequence of the near-mutual exclusivity between TERT expression and markers of ALT." (PMID 34486523, 2021). "Interestingly, HBV/HDV related HCC harbored less frequent HBV insertion in cancer drivers gene such as the TERT promoter compared to HBV alone related HCC." (PMID 33922394, 2021). "It would be important to investigate whether TERT is regulated by MRRs that transit into active enhancers in cancer cells." (PMID 33514712, 2021). "Thus, the assessment of anti-TERT CD4 Th1 cell immunity in circulating lymphocytes has been used as a tool for monitoring antitumor CD4 Th1 response in cancer patients." (PMID 34144673, 2021). "In addition to TERT-CLPTM1L and HLA, 9q34.2, 10q24.33, 12q24.12, and 17q12 have been implicated in susceptibility for multiple cancer types." (PMID 33579919, 2021). "Despite continuing research on TERT-p mutation in human cancers, including a recent study describing the varying frequency of TERT-p mutation in SCCs arising from various organs, TERT-p mutation in penile SCC has not been investigated to date." (PMID 33635430, 2021). "Activation of TERT expression promoted cell proliferation without telomere shortening and was linked to cancer hallmark behaviors in several solid cancers." (PMID 34221969, 2021). "Telomerase reverse transcriptase (TERT) is a part of telomerase closely related to cancer, and higher TERT expression in tumors can predict the poor prognosis of various cancers." (PMID 34926575, 2021). "For example, in a nodule that contains both RAS and TERT promoter mutations, inability to detect TERT would yield an isolated RAS-positive test result, which would indicate a moderate probability of a low-risk cancer." (PMID 32948110, 2021). "Interestingly, there is a significant positive correlation between telomerase reverse transcriptase (TERT) and tRNA levels in cancer." (PMID 34660690, 2021). "Widespread transcriptional reactivation of TERT in cancer is driven by a variety of factors." (PMID 34486523, 2021). "TERT expression and telomerase activation play a crucial role in cancer induction and progression." (PMID 35223454, 2021). "For mutations in noncoding regions, we focused on mutations in the promoter region of known cancer driver genes, and we did not detect mutations in any of these genes including TERT in our patient cohort." (PMID 33536423, 2021). "However, TERT expression is re-activated in 90% of cancers, granting them potential to proliferate indefinitely." (PMID 33599797, 2021). "Strikingly, cancer stemness, a measure reflecting the overall similarity in self-renewal between cancer cells and embryonic stem cells, correlates significantly better than TERT expression with telomerase activity (Rho = 0.85, P = 2e − 9)." (PMID 33420056, 2021). "By contrast, TERT promoter (TERT-p) mutations have not been detected or have been detected at very low frequency in malignant tumors of other organs." (PMID 33635430, 2021). "The hypermethylation pattern of TERT promoter is unique to human cancer and might be useful as a cancer diagnosis and also as a prognostic biomarker but further research, including large cohorts of patients, is required for future clinical application." (PMID 33802026, 2021). "Epigenetic studies in ESC differentiation could indicate whether DNA methylation or histone modification contribute to this process and might also help our understanding of TERT regulation in telomerase-positive cancer cells." (PMID 33802026, 2021). "However, we found that the HG-induced increased expression of KLF4 significantly decreased the expression of TERT in HUVECs, which is inconsistent with previous observations in stem cells and cancer cells." (PMID 34744738, 2021).